EP300 (EP300 lysine acetyltransferase)
Diseases named in the same sentence as EP300 in open-access papers (continued):
Sharing a sentence is not in itself a finding about the gene and the disease.
squamous cell carcinoma (9 papers, 2014 to 2024). A carcinoma arising from squamous epithelial cells. "Additionally, mutations in CREBBP/EP300 are associated with recurrence following radiation in squamous cell carcinoma cohorts." (PMID 34732714, 2021). "They found novel somatic mutations in the MAPK1 gene (8%), HLA-B gene (9%), EP300 (16%), FBXW7 (15%), NFE2L2 (4%), and ERBB2 (6%) of 79 squamous carcinomas, and ELF3 (13%) and CBFB (8%) mutations in 24 adenocarcinomas." (PMID 26701206, 2016).
atherosclerosis (8 papers, 2013 to 2025). A disease characterized by the build-up of fatty material and calcium deposition in the arterial wall resulting in partial or complete occlusion of the arterial lumen. "STAT1 activity is regulated by EP300-dependent acetylation, and that the interaction between EP300 and STAT1 participates in oxidized low-density lipoprotein uptake and foam cell formation, which are responsible for the pathogenesis of atherosclerosis." (PMID 34112215, 2021).
preeclampsia (8 papers, 2013 to 2025). Preeclampsia is a hypertensive disorder of pregnancy that is characterized by new-onset hypertension with proteinuria presenting after 20 weeks of gestation, and depending on mild or severe forms may initially present with severe headache, visual disturbances, and hyperreflexia. "EP300 mutations have been associated with preeclampsia in women carrying a pregnancy affected by RSTS; skin involvement and a mild phenotype in skeletal abnormalities and neuropsychiatric issues are described." (PMID 25599811, 2015). "In addition, we identified that the transcription factor EP300 (E1A binding protein p300) is connected with the largest number of preeclampsia-associated TFs in an extended interaction network." (PMID 23785430, 2013). "Fetuses with mutations in EP300 are predisposed to IUGR, and their mothers are at increased risk of preeclampsia, both of which are indications for medical induction of preterm labour." (PMID 41168876, 2025). "Higher predicted expression of 12 genes (including ATG16L1, BECN1, EP300, SGK1) was associated with increased odds of preeclampsia, while higher predicted expression of 17 genes was associated with decreased risk." (PMID 41220585, 2025). "The 388-gene preeclampsia meta-signature offers a vital starting point for further studies into the relevance of these genes (in particular CREBBP/EP300) and their concomitant pathways as biomarkers or functional molecules in preeclampsia." (PMID 26171964, 2015). "Preeclampsia was reported in mothers of RTS patients with both CREBBP and EP300 mutations." (PMID 26788536, 2016). "Even though CREBBP/EP300 were not identified as DEGs in the other two published meta-analyses, their involvement in preeclampsia was suggested based on association with differentially expressed transcription factors by Vaiman and colleagues." (PMID 26171964, 2015). "If we translate these observations and our meta-analysis results to non-RSTS women, it appears that decreased CEBBP/EP300 levels are detrimental for placenta functioning, resulting in an increased probability for the mother to develop preeclampsia." (PMID 26171964, 2015).
asthma (7 papers, 2014 to 2025). "The levels of EP300 were substantially higher while the levels of histone deacetylases (HDACs) were much lower in asthma." (PMID 35645813, 2022). "In our study, EP300, ID1, ID3, SMAD2, and SMAD5 were DC with a loss of connectivity, whereas SMAD7 exhibited a network connectivity gain due to asthma." (PMID 34257337, 2021).
autism (7 papers, 2016 to 2025). Persistent deficits in social interaction and communication and interaction as well as a markedly restricted repertoire of activity and interest as well as repetitive patterns of behavior. "Two studies included in this review reported on autism in small groups of individuals carrying novel EP300 variants." (PMID 35730128, 2022). "Menke and Hennekam analyzed 11 patients with CREBBP mutations and 2 with EP300 homologous region variants, who lacked typical RSTS features but exhibited developmental delay, autism-like behaviors, short stature, and microcephaly (DDD study, 2018)." (PMID 40672389, 2025). "Additionally, we observed an enrichment (FDR = 0.015) for candidate autism genes, including FOXP1, CUL7, ANK3, and EP300, among the differentially expressed genes." (PMID 34657631, 2021).
cardiomyopathy (7 papers, 2013 to 2024). A disease of the heart muscle or myocardium proper. "Although the role of EP300, in concomitance with Gata4, has been elucidated in cardiac hypertrophy, its role in cardiomyopathies remains highly elusive." (PMID 34445422, 2021). "Collectively, the JAK-STAT pathway may signal to reduce the transcriptional activity of EP300 (i.e., increased T887 phosphorylation) and the expression of FHL1/SLIM, which is implicated in protein turnover and cardiomyopathy." (PMID 38389037, 2024).
depression (7 papers, 2021 to 2025). "Among the 24 potentially causal immunological biomarkers identified for depression, genetically proxied expression of EP300 in blood satisfied the tier A criteria (p = 2*10−09, H4 > 0.8)." (PMID 40281223, 2025). "From these 50 pathways, only the thyroid hormones signaling pathway (based on RXR alpha and EP300 target genes) was found to be overlapped to major depression." (PMID 39457478, 2024). "Among GWAS genes that interacted the most with depression portrait genes were the histone acetyltransferase, EP300, the Rho GTPase, RHOA, the heat shock protein HSPA1A, the dopamine receptor, DRD2, the glutamate receptor, GRM5, the huntington gene, HTT, and the estrogen receptor, ESR2." (PMID 33589676, 2021). "In the PPI network, DPP4, CYP3A4, EP300 MGAM and NR1H4 showed higher degrees and were identified as essential genes of intestinal microbiota influencing the occurrence of depression through the brain–gut axis." (PMID 37433869, 2023). "In conclusion, the intestinal microbiota can affect the development of depression through the metabolites equol, genistein and quercetin, which act on the critical targets of DPP4, CYP3A4, EP300, MGAM and NR1H4." (PMID 37433869, 2023).
sarcoma (7 papers, 2020 to 2026). A usually aggressive malignant neoplasm of the soft tissue or bone. "SRSF3 regulates multiple cancer-related genes, including EP300, DDX5, and MAP4K4, to increase the proliferation of sarcoma cells." (PMID 37558679, 2023).
epilepsy (6 papers, 2016 to 2024). A brain disorder characterized by episodes of abnormally increased neuronal discharge resulting in transient episodes of sensory or motor neurological dysfunction, or psychic dysfunction. "EP300 may serve as potential targets for the treatment of epilepsy based on gene expression profile analysis of brain tissue of patients with epilepsy." (PMID 31214268, 2019). "Interestingly, it has been reported that Fgf2, Creb, and Ep300 are involved in pathogenesis of epilepsy which is susceptive in offspring from preeclamptic mothers." (PMID 25575681, 2016).
Ewing sarcoma (6 papers, 2021 to 2025). A small round cell tumor that lacks morphologic, immunohistochemical, and electron microscopic evidence of neuroectodermal differentiation. "Notable examples include iCBP4 (derived from CCS1477), which selectively targets EP300/CBP in Group 3 MB, and the bromodomain inhibitor iP300w, which prevents P300/CBP-mediated histone acetylation, thereby disrupting EWS::FLI1-driven oncogenic signaling in Ewing sarcoma." (PMID 41228232, 2025).
medulloblastoma (6 papers, 2011 to 2024). A malignant, invasive embryonal neoplasm arising from the cerebellum. "We identify that the high-risk pediatric embryonal brain tumor medulloblastoma (MB) is exceptionally sensitive to EP300/CBP BRD inhibition, compared with HAT domain inhibition." (PMID 38664416, 2024). "For instance, EP300 encodes a histone acetyltransferase protein that activates the expression of genes critical for the development and progression of medulloblastoma." (PMID 37745846, 2023). "Our findings identify specific tumor contexts to examine domain-specific inhibition of EP300/CBP, and provide structural and molecular bases for EP300/CBP BRD inhibition in high-risk, Group 3 medulloblastoma." (PMID 38664416, 2024). "Here, the authors demonstrate lineage-specific sensitivities to domain-specific inhibition of EP300/CBP proteins across cancer and link these effects in group 3 medulloblastoma to control of a transcriptional dependency network." (PMID 38664416, 2024). "Hereto, we performed knockdown of either CREB1, CREBBP, or EP300 in MED8A cells, an in vitro model for Group 3 medulloblastoma and subsequently determined their sensitivity to the chemotherapeutic agent Etoposide." (PMID 34373489, 2021). "To explore a role for CREB-complexes in medulloblastoma, we first investigated the relationship between CREBBP and EP300 mRNA expression and overall survival." (PMID 34373489, 2021). "We then grouped the medulloblastoma samples into below (or above) average pCREB Ser133 (pCREB Ser133 hi/lo), in combination with below (or above) average CREBBP (CREBBPhi/lo) or EP300 (EP300hi/lo) mRNA levels, and assessed their relationship with overall survival." (PMID 34373489, 2021).
microcephaly (6 papers, 2016 to 2025). A congenital or acquired developmental disorder in which the circumference of the head is smaller than normal for the person's age and sex. "In this study, both patients with EP300 gene mutations exhibited short stature and dysmorphic features (e.g., microcephaly, downslanting palpebral fissures, micrognathia, broad nasal bridge), but no typical “grimacing smile” or broad/angulated thumbs." (PMID 40672389, 2025). "Some other studies also found more severe microcephaly and facial bone structure deformities in children with the variants in the EP300 gene." (PMID 37085840, 2023). "Tcf4 binds together with microcephaly-associated transcription factors Smad4, Sox2, Chd7 and Ep300 to active enhancers at primary microcephaly genes Mcph1 and Wdr62." (PMID 28375211, 2017).
myeloid leukemia (6 papers, 2014 to 2025). A clonal proliferation of myeloid cells and their precursors in the bone marrow, peripheral blood, and spleen. "The median quantities of BMPR2, EP300, and TNFAIP3 expression in the myeloid leukemia cell lines are 0.10%, 0.56%, and 0.34%, respectively." (PMID 25364581, 2014). "The relative expression levels of BMPR2, EP300, and TNFAIP3 mRNA in cell lines from myeloid leukemia were significantly lower than those in the cells from the healthy people (P<0.05)." (PMID 25364581, 2014). "In this study, quantitative reverse transcription polymerase chain reaction (qRT-PCR) was used to analyze the expression levels of BMPR2, EP300, TGFβ2, and TNFAIPI3 in B-lymphoma and myeloid leukemia cell lines." (PMID 25364581, 2014). "The expression levels of BMPR2, EP300, and TNFAIP3 mRNA in B-lymphoma cells were significantly higher than those of the myeloid leukemia cells (P<0.05)." (PMID 25364581, 2014). "Meanwhile, the expression levels of BMPR2, EP300, and TNFAIP3 mRNA in myeloid leukemia cells were significantly lower than those of healthy people." (PMID 25364581, 2014). "Results indicate that the expression levels of BMPR2, EP300, and TNFAIP3 mRNA in myeloid leukemia cell lines were significantly lower than those of healthy people or B-malignant cell lines." (PMID 25364581, 2014). "The expression levels of BMPR2, EP300, and TNFAIP3 mRNA in cell lines from myeloid leukemia were significantly lower than those in the cells from the healthy control (P<0.05)." (PMID 25364581, 2014). "Indeed, the pleiotropic gene set was found to have an overrepresentation of regulators of myeloid leukemia: DOT1L, EP300, FLI1, GSE1, and MED24 (OR = 7.1; phypergeometric = 4 × 10−4)." (PMID 38308367, 2024). "Although BMPR2, EP300, TGFβ2, and TNFAIPI3 have been studied in lymphoma or leukemia, no report has compared the expression of the four genes among B-lymphoma cells, the healthy control, and myeloid leukemia." (PMID 25364581, 2014). "BMPR2, EP300, and TNFAIP3 mRNA have been observed to be almost absent in myeloid leukemia cell lines." (PMID 25364581, 2014).
NUT carcinoma (6 papers, 2016 to 2026). "Emerging preclinical studies suggest that molecular heterogeneity, including alterations in epigenetic regulators such as EP300, may influence treatment sensitivity in NUT carcinoma." (PMID 41541495, 2026).
Rubinstein-Taybi syndrome 2 (6 papers, 2022 to 2025). "in EP300, the gene where truncating variants are associated with Rubinstein-Taybi syndrome 2 (RSTS2) (OMIM: 613684)." (PMID 38751117, 2024). "Variants in EP300, mostly in the HAT domain, are associated with Rubinstein Taybi 2 syndrome (RTS2, OMIM 613684)." (PMID 35885957, 2022).
colitis (5 papers, 2021 to 2022). Inflammation of the colon. "Moreover, we applied an inhibitor of EP300, C646, to suppress the activity of EP300 in vivo, and this treatment significantly alleviated colitis in mice." (PMID 34112215, 2021). "Therefore, a decrease in H3K27 acetylation induced by inhibiting EP300 alleviates DSS-induced colitis in mice." (PMID 34112215, 2021). "We found that p-STAT1 binds to EP300 to regulate the expression of LCP2 and TNFAIP2 by promoting H3K27 acetylation at enhancers, and thus, we further investigated whether the increase in H3K27ac levels mediated by EP300 is involved in the development of colitis in mice." (PMID 34112215, 2021).
Cornelia de Lange syndrome (5 papers, 2016 to 2025). A rare syndrome characterized by low birth weight, delayed growth, intellectual disabillity, behavioral problems, and a distinctive facial appearance (thin, arched eyebrows, low set ears, small teeth, and small nose). "Notably, EP300-associated RSTS2 demonstrates substantial phenotypic overlap with multiple Mendelian disorders, including Floating-Harbor syndrome (FHS; OMIM #136140), Cornelia de Lange syndrome (CDLS; OMIM #122470), and Wiedemann-Steiner syndrome (WDSTS; OMIM #605130) and others." (PMID 41347065, 2025).
endometriosis (5 papers, 2016 to 2025). The growth of functional endometrial tissue in anatomic sites outside the uterine body. "The results indicated that 13 TFs were identified in both SLE and endometriosis, and 6 of them (EP300, TCF12, CTCF, POLR2A, CEBPB and NFIC) can act on four potential co-diagnostic genes simultaneously." (PMID 39744159, 2025).
endothelial dysfunction (5 papers, 2022 to 2025). In vascular diseases, endothelial dysfunction is a systemic pathological state of the endothelium (the inner lining of blood vessels) and can be broadly defined as an imbalance between vasodilating and vasoconstricting substances produced by (or acting on) the endothelium. "Its suppression following A-485 treatment suggests a novel axis through which EP300 potentiates endothelial dysfunction in PAH." (PMID 41402732, 2025). "Together, these findings support a mechanistic model in which EP300 promotes endothelial dysfunction in PAH through epigenetic activation of NRP1." (PMID 41402732, 2025). "Gain- and loss-of-function experiments have confirmed that EP300 transcriptionally activates NRP1, promoting endothelial dysfunction in PAH." (PMID 41402732, 2025). "To further elucidate the mechanistic role of EP300 upregulation and its association with H3K27 acetylation in PAH-PAECs, we next examined its functional contribution to endothelial dysfunction." (PMID 41402732, 2025). "Here, we identify EP300 as a key chromatin regulator that promotes endothelial dysfunction in PAH through H3K27ac-dependent activation of NRP1, a coreceptor for VEGFR2 involved in vascular permeability, inflammation, and remodeling." (PMID 41402732, 2025). "Given that endothelial dysfunction is a key early driver of pulmonary vascular remodeling, our findings identify EP300-mediated histone acetylation as a critical upstream event that may initiate and exacerbate disease progression." (PMID 41402732, 2025). "To determine whether NRP1 mediates EP300-induced endothelial dysfunction, we overexpressed EP300 alone or in combination with the NRP1 inhibitor EG00229 in FD-PAECs and assessed endothelial cell proliferation and oxidative stress." (PMID 41402732, 2025).
nasopharyngeal carcinoma (5 papers, 2012 to 2025). A carcinoma arising from the nasopharyngeal epithelium. "The engagement of EP300 in EMT was further observed in nasopharyngeal carcinoma, where p300 promoted EMT through the acetylation of Smad2 and Smad3 in the TGF-β signaling pathway." (PMID 36674511, 2023).
oral cancer (5 papers, 2016 to 2023). "In the present study, we demonstrated that LINC00941 promoter H3K27ac modification mediated by EP300 elevated LINC00941 expression in oral cancer cells." (PMID 32691935, 2020). "Examinations on clinical samples exhibited that MMP-9, CREBBP, and EP300 were significantly increased in oral cancer tissues." (PMID 26980735, 2016).
renal carcinoma (5 papers, 2015 to 2025). A carcinoma arising from the epithelium of the renal parenchyma or the renal pelvis. "BCL3 and EP300 as prognostic factors for KIRC, and upregulated RUNX1 is closely associated with renal cancer progression." (PMID 38292868, 2024).
steatosis (5 papers, 2016 to 2025). Increased lipid within the cytoplasm of cells. "•The listed gene EP300 together with the neighbors, of the network analysis, can be used for the development of biomarker screening tools for the early detection of drug-induced steatosis or other forms of toxicity, also by using other cell types." (PMID 29201983, 2018). "The data presented in this DIB demonstrate induced steatosis pathways by all DMRs during VPA-treatment, covering interesting drug-induced steatosis genes (persistent DMRs upon terminating VPA treatment and the EP300 network)." (PMID 29201983, 2018).
Autoimmunity (4 papers, 2015 to 2019). The occurrence of an immune reaction against the organism's own cells or tissues. "A conditional deletion of Ep300 (which encodes p300) in Treg cells compromises Treg suppressive capability and leads to autoimmunity at around 10 weeks of age." (PMID 31681337, 2019).
brain tumors (4 papers, 2012 to 2024). "Besides, five additional inputs were found after searching for alterations in BCOR, BCORL1, EP300, TRAP1, CREBBP, and L3MBTL2 in the repository of 23 published studies on neuroepithelial brain Tumors including 7207 samples of 6761 patients." (PMID 38637838, 2024).
chronic obstructive pulmonary disease (4 papers, 2021 to 2025). A chronic and progressive lung disorder characterized by the loss of elasticity of the bronchial tree and the air sacs, destruction of the air sacs wall, thickening of the bronchial wall, and mucous accumulation in the bronchial tree. "In turn, the inhibition of the two interactions of DDIT3 identified by MuXTalk, CUL1 and EP300, has been shown to reduce fibroblast proliferation in chronic obstructive pulmonary disease (COPD) and IPF." (PMID 37953325, 2024).